CD36 (CD36 molecule (CD36 blood group))
Diseases named in the same sentence as CD36 in open-access papers (continued):
Sharing a sentence is not in itself a finding about the gene and the disease.
hypertriglyceridemia (21 papers, 2008 to 2024). A laboratory test result indicating elevated triglyceride concentration in the blood. "CD36-deficient patients were shown to have hypertriglyceridemia, whereas patients with acute coronary syndrome exhibited 6-fold higher levels of CD36 in circulating monocytes compared to healthy controls." (PMID 24965703, 2014). "In mouse models, CD36 deficiency impairs intestinal lipid secretion and results in hypertriglyceridemia and others show that CD36 deficiency rescues lipotoxic cardiomyopathy." (PMID 23236364, 2012). "In addition, people with CD36 deficiency develop postprandial hypertriglyceridemia, IR, and cardiovascular disease through enhanced lipoprotein remnant levels in plasma." (PMID 36817150, 2023). "Considering that the major phenotype of global CD36 knockout mice and humans born with CD36 deficiency is hypertriglyceridemia, we are curious whether similar effects will also be seen in humans treated with anti-CD36 therapy." (PMID 37371076, 2023). "Sustained postprandial hypertriglyceridemia is characteristic of the CD36 deficient mouse and there is evidence that it might also occur in humans with CD36 deficiency." (PMID 26727015, 2016). "These functions of CD36 may explain why its deficiency in humans and rodents associates with production of a larger proportion of smaller chylomicron particles that persist in the circulation resulting in postprandial hypertriglyceridemia." (PMID 26727015, 2016). "It has also been shown that endogenous GCs induce hepatic lipid accumulation and hypertriglyceridemia in pregnant mice by activating GR and its target gene, hepatic fatty acid translocase CD36, to accelerate fatty acid uptake in hepatocytes." (PMID 39596881, 2024). "Our findings demonstrate that a selective down regulation of CD36 in the intestine reduces lipid intake and is beneficial to postprandial hypertriglyceridemia." (PMID 22662181, 2012). "The results presented here implicate that Ifrd1 and Ifrd2 play a up to now unknown role in the regulation of Cd36 and therefore possibly contribute to Cd36-related pathogenesis of human metabolic diseases, such as hypoglycemia, hypertriglyceridemia, and disordered fatty acid metabolism." (PMID 37603466, 2023). "Consistent with our findings, Drover and colleagues have shown that CD36 deficiency impairs intestinal lipid processing, leading to secretion defect and then hypertriglyceridemia, and another group led by Ibrahimi discovered that overexpressing CD36 could reduce plasma TG." (PMID 35656026, 2022). "Similarly, evidences supporting a role of CD36 in intestinal fat absorption are accumulated, but contradictory observations have also been reported concerning its direct implication in intestinal lipid trafficking and the control of postprandial hypertriglyceridemia." (PMID 22662181, 2012). "Thus, high level of serum PCSK9, promoting VLDL-R and CD36 degradation, could also contribute to elevated serum VLDL–cholesterol and FFA level leading to hypertriglyceridemia found in lipectomized rats." (PMID 30483910, 2019). "Thus abnormal intestinal CD36 function in early stages of lipid absorption delays the increase in capacity of jejunal lipid absorption and impacts postprandial hypertriglyceridemia without affecting net lipid intestinal absorption." (PMID 26727015, 2016).
liver cancer (21 papers, 2015 to 2025). An epithelial or non-epithelial malignant neoplasm that arises from the liver. "Palmitoylation of CD36 enhances FA uptake and CD36/Fyn/Lyn complex formation, thereby promoting the development of liver cancer." (PMID 40814339, 2025). "Further validation utilizing a liver cancer cell line, HepG2, cultured under conditions with exogenous palmitic acid, shows upregulation of both CD36 mRNA expression and protein palmitoylation." (PMID 34095144, 2021). "Having found an association between the fatty acid uptake protein CD36 and EMT regulators, we sought to study the effects of fatty acids themselves on the metastatic behavior of liver cancer cells." (PMID 26424075, 2015). "Furthermore, the xenograft metastasis mouse model demonstrated that anti-miR-3180 promoted the lung metastasis of MHCC-97H liver cancer cells, whereas CD36 or SCD1 knockdown abrogated it." (PMID 37041584, 2023). "Besides, CD36 expression on PBMCs was positively correlated with the incidence of liver cancer metastasis." (PMID 36184646, 2022). "We then investigated the biomarker potential of CD36 in liver cancer patients." (PMID 36184646, 2022). "Altogether, our study suggests that CD36, by activating glycolysis through Src/PI3K/AKT/ mTOR signaling pathway, could be a critical step in the development and progression of HCC; thus, CD36 may be a novel target for liver cancer therapy." (PMID 33771982, 2021). "Hence, OF exhibits strong effect on anti‐lipid accumulation and anti‐liver cancer formation in CD36 transgenic zebrafish larvae model." (PMID 33377648, 2020). "Additionally, inhibition of CD36 resulted in reduced migration in liver cancer cells, confirming a critical role of the fatty acid uptake protein in the progression of the EMT program." (PMID 26424075, 2015). "Finally, the inhibition of CD36 with SSO reduced migration rates in PA treated cells, confirming the importance of CD36 in mediating PA induced EMT in the liver cancer cells." (PMID 26424075, 2015). "Therefore, by affecting liver inflammation and fibrosis, FAT/CD36 may facilitate the progression of liver cancer." (PMID 41458968, 2025). "In those studies, the treatment of human liver cancer cell lines with FFAs exacerbated the EMT phenotype, whereas chemical inhibition of CD36 mitigated these effects." (PMID 34073989, 2021). "Prior progressing into liver cancer, non-alcoholic steatohepatitis (NASH) features abnormal lipid metabolism with palmitoylated CD36 upregulation." (PMID 34095144, 2021). "Palmitoylated CD36 enhances long-chain fatty acid binding and uptake but lowers FAO through AMPK pathway resulting in lipid accumulation in liver cancer cells." (PMID 34095144, 2021). "In this line of evidence, it has been recently suggested that treatment of human liver cancer cell lines with FFAs exacerbate the EMT phenotype, whereas chemical inhibition of CD36 mitigated these effects." (PMID 28970582, 2017). "Treatment of human liver cancer cell lines with FFAs exacerbated the EMT phenotype, whereas chemical inhibition of CD36 mitigated these effects." (PMID 26424075, 2015). "Although the transcriptomic signature of CD36+ cells does not strongly associate with EMT, FA uptake by CD36 and by the FA-binding proteins 1 and 4 (FABP1 and FABP4) induces EMT in liver cancer cells, thereby increasing their migration and invasion in in vitro assays." (PMID 29739810, 2018). "Additionally, no gene sets were enriched in low CD36 group; however 27 gene sets were enriched in the high CD36 group and 10 out of the 27 significant gene sets are liver cancer signatures, lending further support to the specific role of CD36 in liver cancer independent of BMI." (PMID 26424075, 2015).
myocardial infarction (21 papers, 2012 to 2026). Gross necrosis of the myocardium, as a result of interruption of the blood supply to the area, as in coronary thrombosis. "Unfortunately, platelet CD36 translates atherogenic lipid stress into an increased risk of thrombosis, myocardial infarction, and stroke." (PMID 40565598, 2025). "This adjustment allowed us to evaluate the independent effects of CD36 gene variants and oxidative biomarkers on myocardial infarction risk." (PMID 40867895, 2025). "By contrast, the impairment of the phagocytic capacity of animal macrophages caused by reducing CD36 levels through matrix metalloproteinase (MMP-9)-dependent signaling leads to higher mortality in post-myocardial infarction." (PMID 37239003, 2023). "In CVDs, there is a piece of evidence that PCSK9 is related to myocardial infarction caused by platelet activation through CD36 while these factors are found in various organs and behave differently." (PMID 34307504, 2021). "In another study based on 1,375 patients with coronary heart disease, one SNP in CD36, rs3211956, was significantly associated with acute myocardial infarction as compared with stable coronary disease (allele frequency 11% vs. 8%, p = 0.04)." (PMID 23249574, 2012). "Our other studies on the CD36 region encoding the receptor domain participating in oxLDL and long-chain fatty acid (LCFA) binding and metabolism show that in patients with early-onset CAD, the rs3173798 in the CD36 gene is linked to the risk of myocardial infarction at an earlier age." (PMID 37239003, 2023). "The clinical relevance of the CD36 signaling pathway in thrombotic vascular disease is evidenced by human genetic studies identifying polymorphisms in the CD36 gene that are strongly associated with platelet surface CD36 expression and risk of acute myocardial infarction." (PMID 35624860, 2022). "Previous studies have shown that PCSK9 enhances thrombosis after acute myocardial infarction (AMI) by binding to platelet CD36, leading to increased MI size." (PMID 41573336, 2026). "After myocardial infarction, myocardial remodelling is influenced by overexpressed CD36-mediated Ca2+-dependent platelet activation." (PMID 40565598, 2025). "It analysised at the single-cell level how CD36 palmitoylation couples abnormal lipid metabolism with mitochondrial quality control, providing a new strategy for treating myocardial infarction by targeting metabolic reprogramming." (PMID 41403700, 2025). "In the myocardial infarction (MI) model, CD11b+ and CD36+ macrophages also express VEGFC to promote cardiac lymphangiogenesis and protect cardiac function." (PMID 36831512, 2023). "Previous studies have also shown that the SR CD36 is susceptible to cleavage during atherosclerosis and by MMP-9 after myocardial infarction and our own work recapitulates these findings." (PMID 29163503, 2017). "They found that CD36 activated a series of signaling pathways and thus enhanced platelet activation and myocardial infarction expansion, indicating that CD36 may affect thrombosis in vivo." (PMID 40040886, 2025). "In addition, CD36-mediated thrombosis and NLRP3 inflammasome-mediated autophagy are both associated with the effect of PCSK9 on myocardial infarction prognosis." (PMID 36970356, 2023). "Indeed, it was found that CD36 (a phagocytic marker in macrophages) was reduced post-myocardial infarction in animals treated with an MMP-9 inhibitor but increased post-myocardial infarction in MMP-9 knockout mice." (PMID 31461880, 2019). "However, the role of CD36-mediated defective efferocytosis in exacerbating cardiac function after myocardial infarction remains unclear, as CD36 is a multifunctional protein." (PMID 41590849, 2025). "When myocardial infarction occurs, PCSK9 promotes the generation of ROS and activates CD36 in platelets, resulting in microvascular obstruction and enlarged infarct size." (PMID 36970356, 2023).
myocardial infarction (continued). "Furthermore, specific cardiomyocyte deletion of CD36 has shown to improve cardiac recovery post-myocardial infarction (MI) by redirecting cardiac metabolism toward glucose utilization." (PMID 33262707, 2020). "The study found that CD36 mRNA expression significantly increased in cardiomyocytes after myocardial infarction, but its protein level did not increase proportionally due to post-transcriptional regulation." (PMID 41403700, 2025). "Specifically, CD36 binds to PS, and the absence of CD36 exacerbates cardiac function following myocardial infarction in mice." (PMID 41590849, 2025).
cardiac hypertrophy (20 papers, 2011 to 2025). "Moreover, expression of CD36 has been linked to cardiac hypertrophy, tolerance to ischaemia and diastolic dysfunction in rodent models." (PMID 31141569, 2019). "Immunoblotting results suggested that the impaired expression levels of mitochondrial synthesis-associated proteins (PGC1α, ERRα, PPARα, and CD36) could be partially rescued by AAV9-Sesn2 treatment in aged WT (Aged) mice that had been subjected to pressure overload-induced cardiac hypertrophy." (PMID 32863202, 2020). "As a result, CD36 CKD prevented the development of pressure overload-induced cardiac hypertrophy and dysfunction." (PMID 40027179, 2025). "Meanwhile, CD36 CKD prevented the development of cardiac hypertrophy and cardiac fibrosis, as indicated by smaller heart size, decreased CSA, reduced heart weight/ tibia length and less fibrotic area." (PMID 40027179, 2025). "Alterations in CD36 gene expression may cause some adverse effects on the heart and leads to the disruption of fatty acids or lipid metabolism, resulting in a range of chronic diseases, such as cardiac hypertrophy, heart failure, and cardiac ischemia/reperfusion." (PMID 37109540, 2023). "Genes involved in β-oxidation are downregulated in maladaptive cardiac hypertrophy whereas they (including CD36, a fatty acid translocase and scavenger receptor) are found to be upregulated in exercise-induced cardiac hypertrophy." (PMID 31547508, 2019). "By contrast, increased CD36 expression in middle-aged mice contributes to cardiac hypertrophy, dysfunction and myocardial lipid accumulation." (PMID 26684450, 2016). "The deleterious effect of HFD-induced cardiac hypertrophy and systolic dysfunction was prevented by CD36 suppression." (PMID 26036798, 2015). "The changes in substrate uptake proteins were proportional to disease severity, as an increase in cardiac hypertrophy was accompanied by decreased FAT/CD36 and increased GLUT4." (PMID 22028857, 2011). "The decrease in CD36 in pathological cardiac hypertrophy and the upregulation in physiological cardiac hypertrophy may be related to PPARa." (PMID 40565598, 2025). "Thus, with increasing cardiac hypertrophy there was a shift from FAT/CD36 and electron transport chain complex I protein expression, towards GLUT4 protein expression in the ventricle of patients with aortic stenosis." (PMID 22028857, 2011). "As anticipated, HF fed induced albuminuria, renal hypertrophy (by PAS staining and semi-quantification), and renal fibrosis (by qPCR analysis and IHC staining of TGF-beta 1 and Collagen IV) was attenuated by CD36 peptide treatment." (PMID 37980376, 2023). "In summary, metabolic remodeling follows the progression of cardiac hypertrophy in human HCM and is accompanied by reduction of CD36, decreased dependency on FAO for ATP production, higher myocardial glucose uptake, and lower oxygen consumption." (PMID 31842377, 2019). "The fatty acid translocase/CD36, upregulated in the diabetic heart, is thought to be important in the etiology of cardiac hypertrophy and diabetic cardiomyopathy." (PMID 28933367, 2017). "CD36, which plays a role in the uptake of LCFAs in the myocardium, has been shown to inhibit FAO in cardiomyocytes when knocked out, but this also significantly worsened pathological myocardial hypertrophy." (PMID 38346961, 2024). "Although CD36 is thought to be the main regulator of cardiac FA transport through the plasma membrane, there does not appear to be a consensus on the role of CD36 in pathological cardiac hypertrophy." (PMID 32612538, 2020). "FAT/CD36 and complex I of the electron transport chain were downregulated, whereas the glucose transporter GLUT4 was upregulated with increasing left ventricular mass index, a measure of cardiac hypertrophy." (PMID 22028857, 2011).
cardiac hypertrophy (continued). "Fatty acid oxidation (Acadm, Etfdh, Acadl, Acadvl, Eci1, Hadh, Phyh, Acaa2, Hadha, Hadhb, Cd36), glucose metabolism (Dld, Pdha1, Pgam1, Pgam2, Acss1, Ldhb, Fh1, Slc2a4, Aldh6a1), TCA cycle (Aco2, Dld, Fh1, Ogdh, Sucla2, Sdha, Idh3b, Idh2) were up-regulated by hispidulin in cardiac hypertrophy." (PMID 33324687, 2020). "Moreover, expression of the FA uptake transporter gene, Cd36, is reciprocally downregulated in Lxrα-Tg hearts, which may confer antihypertrophic effects since Cd36 knockout mice are resistant to HFD-induced cardiac hypertrophy." (PMID 26684450, 2016). "In this study, we demonstrated that CD36 CKD, but not CKO, in mice heart, prevented the development of pressure overload-induced cardiac hypertrophy and dysfunction." (PMID 40027179, 2025). "However, unlike the results observed in the CD36 CKO heart, CD36 CKD ameliorated cardiac dysfunction and hypertrophy in the pressure overload heart." (PMID 40027179, 2025).
coronary artery disease (20 papers, 2012 to 2025). "CD36 mutations can cause platelet glycoprotein IV deficiency and increase risk for coronary heart disease." (PMID 32847609, 2020). "It has been reported the protective role of the CD36 polymorphism, G573A, in plaque thickness in patients with early coronary artery disease." (PMID 25006585, 2014). "Also, approximately 17% of Japanese patients with coronary heart disease and 40% of those with hypertrophic cardiomyopathy have CD36 deficiency." (PMID 40565598, 2025). "Furthermore, in the aorta, HFD + A treatment significantly downregulated the expression of adenylyl cyclase-associated protein 1 (CAP1), a human resistin receptor that increases the expression of CD36 mRNA, associated with coronary artery disease." (PMID 35268023, 2022). "The CD36 expression increased in coronary artery disease patients’ monocytes, and statin treatment reduced soluble CD36 and oxLDL uptake." (PMID 40872505, 2025). "Previous study has suggested protective effect of higher soluble CD36 in coronary artery disease patients." (PMID 28303103, 2017). "For example, the scavenger receptors MSR1, CD36, and LOX-1 have been shown to bind modified LDL particles, which play a prominent role in CMD and coronary artery disease." (PMID 25224267, 2014). "We also performed ELISA to investigate the corresponding proteins levels of selected genes and showed that serum levels of SPP1, CD36, ATP6V0D2, CHI3L1, MYH11, and BDNF were differentially expressed in patients with coronary heart disease compared with healthy subjects." (PMID 31682178, 2019).